FGFR1 (fibroblast growth factor receptor 1)
Diseases named in the same sentence as FGFR1 in open-access papers (continued):
Sharing a sentence is not in itself a finding about the gene and the disease.
myocardial ischemia (2 papers, 2013 to 2017). A disorder of cardiac function caused by insufficient blood flow to the muscle tissue of the heart. "FGFR1 was expressed at a relatively constant level from 0.5 to 30 days, but exhibited a transient increase in tyrosine phosphorylation from 1 to 5 days post myocardial ischemia." (PMID 24067542, 2013). "In response to myocardial ischemia/reperfusion injury in the mouse, FGF21 was upregulated and released from the hepatic cells and adipocytes into the circulation and interacted with FGFR1 in cardiomyocytes under the mediation of the cell membrane protein β-Klotho, inducing FGFR1 phosphorylation." (PMID 24067542, 2013). "As FGF21 interacts with all known protein tyrosine kinase-coupled FGFRs, including FGFR1, FGFR2, FGFR3, and FGFR432, 36, 37, we tested the expression of these FGFRs in cardiomyocytes from wild-type mice with and without myocardial ischemia/reperfusion injury." (PMID 24067542, 2013).
neurocytomas (2 papers, 2022 to 2025). "Regarding molecular studies, the FGFR1: TACC1 fusion in neurocytomas is an essential molecular alteration due to its impact on the clinical implications." (PMID 40677455, 2025). "The identification of FGFR1: TACC1 fusions in neurocytomas could provide, in the future, a targeted treatment strategy which may be more effective than traditional therapeutic options." (PMID 40677455, 2025). "This classification was reinforced by the detection of FGFR1: TACC1 fusion, which is a molecular marker which is characteristic of neurocytomas." (PMID 40677455, 2025). "In the present 4 patients, no FGFR1 gene breakage or rearrangement was found by FISH detection, suggesting that sellar/suprasellar neurocytomas may not have the same molecular biological characteristics as those originating from other parts." (PMID 35663322, 2022).
non-alcoholic fatty liver disease (2 papers, 2023). "Recently, evidence has accumulated that Gadd45b deficiency promotes premature aging and skin senescence, and FGFR1 has been reported to ameliorate impaired lipid metabolism in mice with non-alcoholic fatty liver disease through upward regulation of the FGF21/FGFR1 pathway." (PMID 37958806, 2023).
oligodendroglial tumor (2 papers, 2018 to 2022). Oligodendrogliomas are cerebral tumors that are differentiated from other gliomas on the basis of their unique genetic characteristics and better response to chemotherapy. "By additional molecular analyses, BRAF and FGFR1 gene alterations specific to each subgroup were identified: particularly, BRAF alterations in the astrocytic-like group 1 and FGFR1 alterations in group 2, oligodendroglial tumors." (PMID 30279357, 2018).
orofacial cleft (2 papers, 2022 to 2025). A disorder of facial skeleton that is characterized by cleft lip and/or cleft palate that result in feeding, speech and hearing problems caused by failures during development. "Additionally, the development of orofacial clefts is associated with FGFR1 loss-of-function mutations and haploinsufficiency." (PMID 35455561, 2022). "Using peripheral blood, the role of FGFR1 and FGFR2 gene polymorphisms in orofacial cleft development has been researched, furthering the knowledge of orofacial cleft formation." (PMID 35455561, 2022). "Our findings highlight the importance of considering FGFR1 in the molecular diagnosis of isolated SHFM or orofacial clefting, point to the high intrafamilial variability of FGFR1 pathogenic variants, and demonstrate the diagnostic value of targeted NGS in rare congenital malformations." (PMID 40428317, 2025). "Multiple studies have detected FGFR1 and FGFR2 expression in orofacial cleft tissue, therefore indicating a possible role in orofacial cleft morphopathogenesis." (PMID 35455561, 2022). "Even though the dysregulated function of FGFR1, FGFR2 and FOXO1 has been examined in non-syndromic orofacial clefts, there has been limited research regarding the comparison of these factors in one individual’s two separate locations—cleft-affected lip tissue and cleft-affected palatine tissue." (PMID 35455561, 2022). "Additionally, combining different methods to evaluate FGFR2 isoforms and FGFs could greatly impact the understanding of the roles of FGFR1, FGFR2 and FOXO1 in orofacial cleft development." (PMID 35455561, 2022). "Numerous intercorrelations between FGFR1, FGFR2 and FOXO1 do not exclude their role in the possible complex morphopathogenesis in each individual affected by orofacial clefts." (PMID 35455561, 2022).
pancreatic neuroendocrine tumor (2 papers, 2021 to 2024). Pancreatic endocrine tumor, also known as pancreatic neuroendocrine tumor (PNET), describes a group of endocrine tumors originating in the pancreas that are usually indolent and benign, but may have the potential to be malignant. "Inhibiting the FGF pathway with brivanib (a first-class dual inhibitor of VEGR2-3/FGFR1-2-3) in mice with pancreatic neuroendocrine tumors has resulted in promising activity after failure to anti-VEGF treatment." (PMID 34885091, 2021). "Surufatinib (Sulanda® in China) is an oral, small-molecule, anti-VEGFR kinase inhibitor that targets VEGFR-1, -2, and -3, FGFR-1, and colony-stimulating factor-1 receptor (CSF-1R) and was approved in China for the treatment of pancreatic and non-pancreatic neuroendocrine tumors." (PMID 39055564, 2024).
parathyroid adenoma (2 papers, 2019 to 2023). "Notably, a previous study comparing parathyroid adenoma, non‐metastatic and metastatic PC found that FGFR1 is one of the genes overexpressed in metastatic versus non‐metastatic PC, also emphasizing FGFR1 inhibition as a potential therapeutic strategy." (PMID 36808802, 2023).
RASopathies (2 papers, 2019 to 2022). "Postzygotic KRAS, HRAS, NRAS, and FGFR1 mutations result in a group of mosaic RASopathies characterized by related developmental anomalies in eye, skin, heart, and brain." (PMID 30891959, 2019). "Our study allowed the expansion of the clinical spectrum of mosaic RASopathies and supports that somatic mosaicism for recurrent mutations in KRAS and FGFR1 is a commonly involved mechanism in these rare oculocutaneous developmental anomalies." (PMID 30891959, 2019). "Our study allowed the expansion of the clinical spectrum of mosaic RASopathies and supports that mosaicism for recurrent mutations in KRAS and FGFR1 is a commonly involved mechanism in these rare oculocutaneous anomalies." (PMID 30891959, 2019).
rectal cancer (2 papers, 2023 to 2025). A primary or metastatic malignant neoplasm that affects the rectum. "The five most frequently altered potentially targetable genes in colon and rectal cancer were PIK3CA (19.6% and 14.2%), PTEN (8.7% and 5.9%), ERBB2 (4.7% and 6.0%), EGFR (2.5% and 2.0%), and FGFR1 (2.0% and 2.7%)." (PMID 39865537, 2025). "A similar pattern was detectable in rectal cancer, where PIK3CA and PTEN alterations were significantly overrepresented in the RAS/BRAF‐altered subgroup and EGFR, ERBB2, FGFR1, and FGFR3 alterations were significantly overrepresented in the RAS/BRAF‐wt subgroup." (PMID 39865537, 2025).
renal cell carcinoma (2 papers, 2013 to 2025). "The in silico functional analysis showed an association between the FGFR1 molecule and pazopanib, which a tyrosine kinase inhibitor recently approved for the treatment of renal cell carcinomas (RCC)." (PMID 23483937, 2013).
salivary gland tumors (2 papers, 2014 to 2015). "Fibroblast growth factor 2 (FGF2) and fibroblast growth factor receptor 1 (FGFR1) concentrations in saliva are significantly elevated in patients with salivary gland tumors making it a potential biomarker in the early detection of salivary gland tumors." (PMID 24616813, 2014). "The first FGFR fusion observed in epithelial cancers, FGFR1-PLAG1, was found in a subset of pleomorphic salivary gland adenomas, and involves FGFR1 as the 5′ partner upstream of PLAG1, the known driver of salivary gland tumors." (PMID 26684754, 2015).
seminoma (2 papers, 2013 to 2025). A radiosensitive malignant germ cell tumor found in the testis (especially undescended), and extragonadal sites (anterior mediastinum and pineal gland). "Loss of Fgf8 and Fgfr1 expression in Xenopus reduces cilia length and expression of the human orthologs is reduced in seminoma specifically when compared to other GCTs." (PMID 23599692, 2013). "IHC confirmed the marked expression of FGF23 solely in OCT4-positive GCNIS cells that also expressed FGFR1, while Klotho was exclusively expressed in normal germ cells and not found in any of the OCT4-positive cancer cells including seminoma and EC." (PMID 40279260, 2025).
soft tissue neoplasm (2 papers, 2019 to 2022). A benign, intermediate, or malignant neoplasm that arises from the soft tissue. "Other RTKs, such as FGFR1 and AXL in the soft tissue tumors, and FGFR1 and ALK in MB-WNT, showed absolute values in the 90th percentile of all tumors, revealing potential therapeutic susceptibilities." (PMID 35978432, 2022).
spotted fever (2 papers, 2017 to 2018). A type of tick-borne disease which presents on the skin caused by bacteria of the genus Rickettsia. "Employing a coalescence of biochemical, molecular, and pharmacological approaches, we have identified that pathogenic Rickettsia species belonging to the spotted fever group avail the host FGFR1/HSPGs complex to gain entry into target ECs." (PMID 28806774, 2017).
synovial sarcoma (2 papers, 2018 to 2020). "Expression of Fgfr1 and Nedd9, also located near common integration sites, did not accelerate synovial sarcoma development." (PMID 32019274, 2020).
thymoma (2 papers, 2023 to 2024). A neoplasm arising from the epithelial cells of the thymus. "Our findings revealed previously unreported CDC27 and FGFR1 mutations in thymoma." (PMID 37828033, 2023). "On the other hand, alterations in RTK–RAS family signaling cascade were detected only in recurrent thymomas (FGFR1/4, BRAF) (13%)." (PMID 39273507, 2024).
uterine carcinosarcoma (2 papers, 2015 to 2025). A usually aggressive malignant neoplasm arising from the uterine corpus and less often the cervix. "In uterine carcinosarcomas, FGFR1 genomic amplification appear to occur in about 10 % of cases based on c-Bioportal data." (PMID 41202566, 2025). "Overall, the in vivo findings suggest an oncogenic role for highly amplified and highly expressed FGFR1 in uterine carcinosarcoma." (PMID 41202566, 2025). "We have identified a number of molecular alterations that may be targetable using compounds currently under clinical use or under clinical trial study, and demonstrated preclinical evidence in support of targeting amplified/over-expressed FGFR1 in uterine carcinosarcoma." (PMID 41202566, 2025). "Among the previously reported PDX models of uterine carcinosarcomas with available CNV data, FGFR1 genomic amplification was identified in 1 of 5 tumors." (PMID 41202566, 2025).
acute monocytic leukemia (1 paper, 2025). Acute monoblastic leukemia (AML-M5), is one of the most common subtypes of acute myeloid leukemia (AML) that is either comprised of more than 80% of monoblasts (AML-M5a) or 30-80% monoblasts with (pro)monocytic differentiation (AML-M5b). "However, LPS stimulation significantly increases FGFR1 levels in a human monocytic cell line derived from an acute monocytic leukemia patient." (PMID 40538537, 2025).
acute respiratory distress syndrome (1 paper, 2024). Progressive and life-threatening pulmonary distress in the absence of an underlying pulmonary condition, usually following major trauma or surgery. "In some diseases, such as acute lung injury (ALI) or acute respiratory distress syndrome (ARDS), the down-regulation of FGFR1 worsens lung injury, inflammatory infiltrates, and vascular infiltration, which can lead to disease progression." (PMID 40135140, 2024).
ADNP syndrome (1 paper, 2020). "Looking at genes that might be associated with peripheral phenotypes of the ADNP syndrome, FGFR1 showed reduced expression in the cerebellum and hypophysis." (PMID 32661233, 2020).
adrenal tumors (1 paper, 2024). "Contrary to experiences from Europe, Asian patients with PPGL due to PVs in kinase signaling genes NF1, HRAS, and FGFR1 showed a high proportion of sympathetic tumors, while European patients almost exclusively had adrenal tumors (P < .005)." (PMID 38481600, 2024).
adrenocortical carcinoma (1 paper, 2017). "In these seven patients, three PRs (two with FGFR2 fusion-positive iCCA and one with urothelial cancer with FGFR2 and FGF19 amplification) and two durable SDs with tumour reduction (FGFR2 fusion-positive iCCA and adrenocortical carcinoma with FGFR1 amplification) were observed." (PMID 28972963, 2017).
adrenocortical tumors (1 paper, 2021). "Importantly, from the therapeutic potential point of view, the three FGFRs that we could show to be differentially expressed between benign and malignant adrenocortical tumors, FGFR1, 2 and 4, were also confirmed in the larger cohort of FFPE tissues." (PMID 34956100, 2021).
alcohol abuse (1 paper, 2017). The use of alcoholic beverages to excess, either on individual occasions ("binge drinking") or as a regular practice. "FGFR1 amplification was positively associated with alcohol consumption, which strongly implies that FGFR1 amplification is an oncogenic aberration caused by alcohol abuse." (PMID 29179482, 2017). "Our findings suggest that FGFR1 amplification may be a major oncogenic aberration in ESCC that is induced by alcohol abuse." (PMID 29179482, 2017).
alcohol addiction (1 paper, 2023). "We found that Fgf-2 and its main receptor, Fgfr1, play an essential role in the development of alcohol addiction as both promoters show changes in their methylation patterns as well as their gene expression in specific brain areas." (PMID 36834747, 2023). "Nevertheless, less is known about the underlying mechanisms of epigenetic regulation of either Fgf-2 or its main receptor, Fgfr1, in the context of alcohol addiction." (PMID 36834747, 2023).
amenorrhea (1 paper, 2017). The absence of menses in a woman who has achieved reproductive age. "We examined adolescents and young adults with stalled puberty or unexplained amenorrhea for mutations in GNRHR, FGFR1, TAC3, and TACR3 genes." (PMID 29182666, 2017).
anemia (1 paper, 2015). A reduction in the number of red blood cells, the amount of hemoglobin, and/or the volume of packed red blood cells. "Multivariate Cox proportional hazards regression models were constructed for FGFR1 and FRS2α individually, adjusting for baseline Eastern Cooperative Oncology Group performance status, treatment arm and anemia status." (PMID 25900027, 2015). "Multivariate Cox proportional hazards regression models were constructed for FGFR1 and FRS2α individually, adjusting for baseline ECOG performance status, treatment arm and baseline anemia." (PMID 25900027, 2015). "We did not observe an association with FGFR1 intensity with patient characteristics (sex, ethnicity, ECOG performance status, MSKCC prognostic risk category or anemia)." (PMID 25900027, 2015).
ankylosis (1 paper, 2024). Fixation and immobility of a joint. "In summary, our study reveals that Fgfr1 mutation can be responsible for tooth ankylosis, and further shows that FGF signaling regulates progenitor cell fate during tooth root morphogenesis via the FGF-PIEZO2-WNT signaling axis." (PMID 38910207, 2024). "Loss of Fgfr1 in Gli1+ progenitors leads to hyperproliferation and differentiation, which causes narrowed periodontal ligament (PDL) space with abnormal cementum/bone formation leading to ankylosis." (PMID 38910207, 2024).
Arthritis (1 paper, 2008). Inflammation of a joint. "Importantly, ASV derived from VEGF receptor type 1 and Tie1, and to a lesser extent from VEGF receptor type 2 and fibroblast growth factor receptor 1, reduced clinical signs of arthritis in vivo." (PMID 18593464, 2008).